USF1 (upstream transcription factor 1)
Description:
Transcription factor that binds to a symmetrical DNA sequence (E-boxes) (5'-CACGTG-3') that is found in a variety of viral and cellular promoters.
Synonyms: bHLHb11; UEF; MLTFI; FCHL; FCHL1; HYPLIP1; MLTF
Tractability: PROTAC: UniProt records ubiquitination sites on it; ubiquitination databases record sites on it; its protein half-life has been measured.
Gene: Protein-coding gene on chromosome 1 (161,039,249 to 161,045,977, reverse strand). Ensembl gene ENSG00000158773.
Subcellular location: Nucleus
Subcellular location (Human Protein Atlas): Nucleoplasm
Pathways (Reactome):
Developmental Biology: Regulation of MITF-M-dependent genes involved in pigmentation
Signal Transduction: Estrogen-dependent gene expression
Gene Ontology:
Molecular function: bHLH transcription factor binding; DNA-binding transcription activator activity, RNA polymerase II-specific; DNA-binding transcription factor activity, RNA polymerase II-specific; E-box binding; enzyme binding; histone deacetylase binding; identical protein binding; protein binding; protein heterodimerization activity; protein homodimerization activity; protein kinase binding; protein-containing complex binding; sequence-specific DNA binding; sequence-specific double-stranded DNA binding; RNA polymerase II cis-regulatory region sequence-specific DNA binding; DNA binding; DNA-binding transcription factor activity; double-stranded DNA binding; protein dimerization activity
Biological process: cellular response to glucose stimulus; cellular response to insulin stimulus; glucose mediated signaling pathway; late viral transcription; positive regulation of transcription by RNA polymerase II; regulation of transcription by RNA polymerase II; response to hypoxia; carbon catabolite regulation of transcription; glucose homeostasis; lipid homeostasis; negative regulation of fibrinolysis; response to UV; glucose metabolic process; regulation of DNA-templated transcription
Cellular component: chromatin; nucleoplasm; nucleus; transcription regulator complex
Genetic constraint (gnomAD): Loss-of-function variants: 22 observed, 47.76 expected, observed/expected ratio (o/e) 0.46, 90% interval 0.33 to 0.66. The upper end of that interval is the gene's LOEUF score, 0.66, which puts it in group 2 of 6, group 1 being the genes least tolerant of losing a copy. Missense variants: 287 observed, 412.12 expected, observed/expected ratio (o/e) 0.7, 90% interval 0.63 to 0.77. Synonymous variants: 150 observed, 151.99 expected, observed/expected ratio (o/e) 0.99, 90% interval 0.86 to 1.13.
Homologues: Orthologues: chimpanzee USF1 (100% identical), macaque USF1 (100% identical), guinea pig USF1 (99% identical), pig USF1 (99% identical), mouse Usf1 (98% identical), rat Tstd1 (98% identical), rabbit USF1 (85% identical), dog USF1 (78% identical), zebrafish usf1 (59% identical), tropical clawed frog usf1 (51% identical), zebrafish usf1l (44% identical). Paralogues in human: USF2 (55% identical), SREBF2 (28% identical), SREBF1 (27% identical).
Diseases named in the same sentence as USF1 in open-access papers:
USF1 is named in the same sentence as 92 diseases in open-access papers, as found by Europe PMC text mining. Sharing a sentence is not in itself a finding about the gene and the disease. The quoted sentences say what the papers report.
breast carcinoma (16 papers, 2012 to 2026). "Intriguingly, SFN administration to breast cancer cells led to the down-regulation of HDAC5 through the repression of the upstream stimulatory factor-1 (USF1) activity." (PMID 36765652, 2023). "Our study demonstrates the broad contribution of the USF1/ATRAP/PBX3 axis to breast cancer progression and provides a strong potential therapeutic target." (PMID 35414770, 2022). "A growing body of evidence suggests that 1) USF1 is overexpressed in breast cancer cell lines and tissues; 2) USF1 can promote cell proliferation; and 3) USF1 expression is correlated with poor survival outcomes." (PMID 35414770, 2022). "In contrast, MDA-MB-453 and MCF7 breast cancer cells exhibited relative low expression of USF1, ATRAP and PBX3." (PMID 35414770, 2022). "In fact, a positive correlation between ATRAP and USF1 mRNA levels was observed in breast cancer samples from the TCGA database." (PMID 35414770, 2022). "In conclusion, we uncovered a USF1-ATRAP-PBX3-AKT/mTOR axis that functions in breast cancer tumor progression both in vitro and in vivo." (PMID 35414770, 2022). "In one research, CircANKS1B was found to be upregulated in TNBC and promoted the metastasis of breast cancer through sponging miR-148a-3p and miR-152-3p, which increases the expression of USF1." (PMID 36052282, 2022). "We found that USF1 expression was significantly upregulated in primary breast cancer tissues compared with that in normal breast tissue." (PMID 35414770, 2022). "Consistent with our observations, the distribution and intensity of ATRAP were both positively correlated with PBX3 and USF1 in breast cancer tissue specimens." (PMID 35414770, 2022). "Based on these findings, we re-examined the role of USF1 in breast cancer cells in publicly available datasets from TCGA." (PMID 35414770, 2022). "The transcription factor USF1 is a recognized breast cancer oncogene that can promote Epithelial‐mesenchymal transition (EMT) via transforming growth factor β1 (TGF‐β1) overexpression leading to stimulation of TGF‐β1/Smad signaling." (PMID 34766130, 2020). "These indicate USF1 can directly bind to TGF-β1 promoter to increase its transcriptional activity in breast cancer cells." (PMID 30454010, 2018). "(D) The distant metastasis-free survival curves in breast cancer patients with low and high USF1 expression from KM-plotter database." (PMID 30454010, 2018). "By a series of screenings and validations, we identified that USF1, the common target of miR-148a-3p and miR-152-3p, participated in circANKS1B-mediated pro-metastasis process in breast cancer." (PMID 30454010, 2018). "And USF1 was positively correlated with TGF-β1 in breast cancer tissues from the TCGA database (r = 0.223, n = 1109, p < 0.001)." (PMID 30454010, 2018). "The results suggested that ATRAP is essential for USF1-mediated breast cancer progression." (PMID 35414770, 2022). "Subsequently, we obtained results consistent with this literature by luciferase fusion reporter assays which confirmed that USF1 directly binds to ATRAP DNA sequence to transactivate its expression in breast cancer and that USF1 levels are positively correlated with ATRAP expression levels." (PMID 35414770, 2022). "(B) The expression of USF1 mRNA in breast cancer tissues from TCGA database." (PMID 30454010, 2018). "These suggest that ESRP1 is also a direct transcriptional target of USF1 in breast cancer." (PMID 30454010, 2018). "In addition, we explored the role of USF1 in breast cancer, and IHC results showed that USF1 was significantly up-regulated in breast cancer tissues, particularly in TNBC, which was also confirmed in TCGA database." (PMID 30454010, 2018). "Importantly, circANKS1B was positively correlated with USF1 in breast cancer tissues (r = 0.572, n = 165, p < 0.001)." (PMID 30454010, 2018). "Thus, we presume that USF1 contributes to breast cancer metastasis by regulating TGF-β1-mediated EMT process." (PMID 30454010, 2018).
breast carcinoma (continued). "In breast cancer cell lines, USF1 and USF2 were expressed, but a significant loss of transcriptional activity of both proteins was observed in approximately 50% of the transformed breast cell lines indicating that loss of USF function favors proliferation." (PMID 25741280, 2015). "Similarly, CircANKS1B promotes breast cancer invasion and metastasis by sequestering miR-148a-3p and miR-152-3p, leading to the upregulation of the transcription factor USF1 and a subsequent increase in TGF-β1 expression, ultimately activating the TGF-β1/SMAD signaling cascade to induce EMT." (PMID 41230432, 2026). "Subsequently, we examined the protein expression levels of USF1, ATRAP and PBX3 in breast epithelial cell (MCF10A) and 7 breast cancer cell lines." (PMID 35414770, 2022). "To further examine the relationship between ATRAP and human breast cancer, we performed IHC staining of ATRAP, PBX3, and USF1 in 49 breast cancer patient specimens." (PMID 35414770, 2022). "circANKS1B increases the expression of transcription factor USF1, which upregulates TGF-β1 expression resulting in activated TGF-β1/Smad signaling and EMT in breast cancer." (PMID 35148692, 2022). "In light of these findings that ATRAP was regulated by USF1, thereby contributing to breast cancer progression, we investigated the effects of USF1 on aggressive behavior in ATRAP-induced breast cancer." (PMID 35414770, 2022). "And a positive correlation between USF1 and ESRP1 expression was observed in breast cancer tissues from TCGA database (r = 0.264, n = 1109, p < 0.001)." (PMID 30454010, 2018). "In our experiments, we demonstrated that inhibition of USF1 expression can reduce breast cancer cell proliferation, movement, and invasion, while ATRAP overexpression can restore the inhibitory effects of USF1 on breast cancer cells." (PMID 35414770, 2022). "Therefore, the USF1/ATRAP/PBX3 axis activates AKT/mTOR signaling and promotes breast cancer aggressiveness." (PMID 35414770, 2022). "Furthermore, we found that in clinic, high levels of ATRAP combined with upregulation of USF1 and PBX3 can serve as a potentially reliable prognostic indicator for breast cancer patient outcomes." (PMID 35414770, 2022). "Moreover, we found that circANKS1B biogenesis in breast cancer was promoted by splicing factor ESRP1, whose expression was also regulated by USF1." (PMID 30454010, 2018).
glioma (14 papers, 2015 to 2025). A benign or malignant brain and spinal cord tumor that arises from glial cells (astrocytes, oligodendrocytes, ependymal cells). "For example, the transcription factor upstream stimulatory factor 1 (USF1) promotes glioma cell invasion and migration by activating the lncRNA hyaluronan synthase 2-AS1 (HAS2-AS1)." (PMID 37225681, 2023). "Increasing evidence has demonstrated that USF1 plays an important role in many cancers, including gastric cancer, glioma, and melanoma." (PMID 36482116, 2022). "Among them, transcription factor USF1 has previously been reported to promote the invasion and migration of glioma cells by activating lncRNAHAS2-AS1." (PMID 36304995, 2022). "The up-regulation of USF1 has been reported to promote multiple solid tumors such as hepatocellular carcinoma, gastric carcinogenesis, and glioma." (PMID 34290570, 2021). "USF1/SNHG16/miR-212–3p/ALDH1A1 and USF1/linc00667/miR-429/ALDH1A1 axis regulates the VM of glioma cells." (PMID 34803608, 2021). "Then, we divided the two glioma cell lines into three groups: si-NC+oe-NC, si-USF1+oe-NC, and si-USF1+oe-HAS2-AS1." (PMID 32776110, 2020). "In glioma, USF1 can increase blood–brain barrier permeability and down-regulate the expression of tight junction protein in glioma microvascular endothelial cells." (PMID 32776110, 2020). "At the same time, we proved that USF1 was significantly highly expressed in glioma tumor tissues and cell lines." (PMID 32776110, 2020). "To verify the effects of USF1 on glioma invasion and migration, we silenced USF1 and overexpressed HAS2-AS1 expression in glioma cell lines U87 and U251." (PMID 32776110, 2020). "The protein expression of USF1 was detected by Western blot and it was found to be highly expressed in glioma cell lines U87 and U251." (PMID 32776110, 2020). "To verify that HAS2-AS1 was activated by USF1 in glioma cells, we obtained the binding sites and the first three binding sequences of USF1 on HAS2-AS1 promoter region using the JASPAR website." (PMID 32776110, 2020). "The results showed that silencing USF1 dramatically inhibited migration and invasion abilities of glioma." (PMID 32776110, 2020). "This knockdown also decreased the levels of tight junction-correlated proteins, such as Zonula occludens 1 (ZO-1), occludin, and claudin-5, in glioma microvascular endothelial cells by targeting upstream stimulatory factor 1 (USF1), thus enabling drug delivery." (PMID 33980320, 2021). "USF1 promotes glioma invasion and migration by activating HAS2-AS1." (PMID 32776110, 2020). "Then, we further detected the expression of USF1 in glioma tissues and cells by qRT-PCR." (PMID 32776110, 2020). "USF1 was highly expressed in glioma and positively correlated with HAS2-AS1." (PMID 32776110, 2020). "The results illustrated that USF1 was significantly highly expressed in glioma tissues and cells." (PMID 32776110, 2020). "qRT-PCR was used to detect the expressions of HAS2-AS1 and USF1 in glioma tissues and cell lines." (PMID 32776110, 2020). "The transcription of HAS2-AS1 was activated by USF1, and the highly expressed HAS2-AS1 contributed to the migration, and invasion of glioma cells." (PMID 35155573, 2022). "The transcription of HAS2-AS1 was activated by USF1 via binding to HAS2-AS1 promoter region, consequently potentiating the invasion and migration abilities of glioma cells." (PMID 32776110, 2020). "Here, this study mined the transcription factor USF1 of HAS2-AS1 through bioinformatics, and explored the influence of HAS2-AS1 on the invasion and migration of glioma cells, which provided a new theoretical basis for the targeted treatment of glioma." (PMID 32776110, 2020). "The expressions of USF1 and HAS2-AS1 are positively correlated, and both are significantly up-regulated in glioma." (PMID 32776110, 2020).
glioma (continued). "Inhibiting the expression of USF1 could reduce the migration and invasion abilities of glioma cells, while overexpressing HAS2-AS1 could recover the inhibitory effects of USF1 on glioma cells to a certain extent." (PMID 32776110, 2020). "In summary, our results demonstrated that both HAS2-AS1 and USF1 were highly expressed in glioma tissues and cells, and USF1 could bind to the HAS2-AS1 promoter region to activate the transcription of HAS2-AS1, thus promoting the migration and invasion of glioma cells." (PMID 32776110, 2020).
atherosclerosis (13 papers, 2010 to 2025). A disease characterized by the build-up of fatty material and calcium deposition in the arterial wall resulting in partial or complete occlusion of the arterial lumen. "Studies have shown that in mice, inactivation of Usf1 significantly improves diet-induced dyslipidemia, obesity, IR, hepatic steatosis, and atherosclerosis, while NASH is associated with IR and increased expression of PPARγ in the liver." (PMID 39840059, 2024). "In conclusion, our bone marrow transplantation study has shown that macrophage USF1 deficiency is associated with the presence of steatohepatitis, aggravated hyperlipidemia, and increased atherosclerosis susceptibility in LDL receptor knockout mice." (PMID 34385562, 2021). "We therefore anticipate that the increase in plasma cholesterol levels represents the driving force behind the aggravated atherosclerosis susceptibility found in USF1 knockout bone marrow recipients." (PMID 34385562, 2021). "In conclusion, we have shown that hematopoietic USF1 deficiency is associated with an increased atherosclerosis susceptibility in LDL receptor knockout mice." (PMID 34385562, 2021). "We investigated sex-specific effects of USF1 gene allelic variants on serum indices of lipoprotein metabolism, early markers of asymptomatic atherosclerosis and their changes during six years of follow-up." (PMID 24722012, 2014). "In the current study we therefore tested whether selective hematopoietic USF1 deficiency can also beneficially impact the development of atherosclerosis." (PMID 34385562, 2021). "This study aims to determine whether USF1 SNPs interact with traditional risk factors of atherosclerosis to increase coronary artery disease (CAD) risk." (PMID 26068452, 2015). "Finally, USF1 deficiency relieved atherosclerosis in ApoE−/− mice through inhibiting EndMT." (PMID 38424494, 2024). "In this study it was shown that selective ablation of USF1 in bone marrow-derived cells, including macrophages, is associated with augmented hypercholesterolemia and foam cell development and a parallel increase in the atherosclerosis susceptibility in LDL receptor knockout mice." (PMID 34385562, 2021). "Herein, we explored the biological function and mechanisms of upstream stimulating factor 1 (USF1) in EndMT during atherosclerosis." (PMID 38424494, 2024). "Taken together, we uncover a USF1/USP14/NLRC5/Smad2/3 axis that drives atherosclerosis progression via inducing EndMT." (PMID 38424494, 2024). "Here, USP14 level was found to be positively correlated with USF1 level in the clinical samples of atherosclerosis." (PMID 38424494, 2024). "Our findings indicate the contribution of the USF1/USP14/NLRC5 axis to atherosclerosis development via promoting EndMT, which provide effective therapeutic targets." (PMID 38424494, 2024). "Our observations suggest USF1 as a prognostic marker, as well as a novel potential therapeutic target for atherosclerosis." (PMID 38424494, 2024). "In contrast to our hypothesis that macrophage USF1 deficiency would attenuate the progress of atherosclerosis, the outcome of ablation of USF1 function in bone marrow cells was actually opposite and associated with a moderately increased atherosclerosis susceptibility." (PMID 34385562, 2021). "We recently showed that inactivation of USF1 in mice protects against atherosclerosis, insulin resistance, obesity, and hepatic steatosis." (PMID 30545366, 2018). "Additionally, USF1 transcriptionally activated USP14 to drive atherosclerosis by promoting EndMT through the NLRC5/Smad2/3 axis." (PMID 40413536, 2025).